GSK3B (glycogen synthase kinase 3 beta)
Diseases named in the same sentence as GSK3B in open-access papers (continued):
Sharing a sentence is not in itself a finding about the gene and the disease.
breast cancer (continued). "For example, nuclear localization of GSK-3β was demonstrated in 70% of human breast carcinomas and 73% of squamous cell head and neck carcinomas, whereas no detectable expression of nuclear GSK-3β was found in benign breast tissue and in benign salivary gland and other benign head and neck tissues." (PMID 36430630, 2022). "Based on the reported PK inhibitory activity of isatin and benzofuran nuclei, specially, on the homologous CDK2 and GSK-3β kinases, a hybridisation strategy of these two privileged scaffolds was adapted to design dual CDK2/GSK-3β hybrid inhibitors which could target breast cancer." (PMID 33327806, 2021). "In xenograft models of breast cancer, poly ADP ribose polymerase (PARP) inhibition was shown to upregulate tumor PD-L1 expression via GSK-3β inactivation, suggesting a potential link between not only GSK-3β with immunomodulation but also with DNA damage response modulation." (PMID 34356465, 2021). "In summary, our current results revealed that SHP-1 significantly inhibits breast cancer cell proliferation and cell invasion and suppresses mammary tumorigenesis in xenografts in mice by directly interacting with EGFR and inhibiting the EGFR/Ras/Erk/GSK3β signaling pathway." (PMID 34591414, 2021). "Since GSK-3β is negatively regulated by the PI3K/Akt axis via phosphorylation at Serine 9 (Ser 9), and (+)-usnic acid was shown to inhibit Akt activity in breast cancer cells, we speculated whether (+)-usnic acid interferes with Nrf2 expression via the PI3K/Akt pathway in LUSC cells." (PMID 32013250, 2020). "Furthermore, GSK-3β specific inhibitor markedly abolished DEX-mediated reduction of TRAIL-induced apoptosis in human renal cancer cells (Caki-1 and A498), human lung cancer cells (A549), and human breast cancer cells (MDA-MB361)." (PMID 33050333, 2020). "Importantly, individual silencing of GSK-3β, APC, or ICAT dramatically increased the rate of cell proliferation and growth, further demonstrating that GSK-3β, APC, and ICAT are essential effectors of miR-1229–induced breast cancer cell proliferation." (PMID 26992223, 2016). "Thus, our results support the relevance of GSK-3β and autophagy as two targets for controlling cell cycle progression and proliferative capacity in MCF7, highlighting the co-treatment of breast cancer cells with 3-MA to synergize the effect of the proteasome inhibition." (PMID 25941117, 2015). "Results from this study also highlight the importance of HER-2/neu or PI3K/Akt components, including GSK-3β, β-catenin, cyclin D1 and p21WAF1, which may serve as future targets for the development of therapeutic strategies against HER-2/neu-overexpressing breast cancer." (PMID 24765191, 2014). "As expected, the phosphorylation of AKT, GSK-3β, PRAS40, S6K and 4E-BP1 was markedly reduced by NVP-BEZ235 but the total proteins of them were not affected in CNE2 and HONE1cells, which was consistent with studies of other tumors, such as breast cancer, gliomas and myeloma." (PMID 23533654, 2013). "To determine whether Bcl-w plays an invasion-promoting role in general, we examined whether the protein enhances p-GSK3β, β-catenin and MMP-2 expression in several types of cancer cells, including U373, U87MG (glioma), MDA-MB-231 (breast cancer) and H1299 (lung cancer)." (PMID 23826359, 2013). "GSK3B silencing could prevent histone H3 phosphorylation and reduce DNMT1 expression, thereby inhibiting the proliferation of breast cancer cells induced by high glucose, and the expression of GSK3B and DNMT1 proteins are in the same direction in breast cancer cells." (PMID 35747513, 2022). "In the present study, we discovered that the cytoplasmic AQP1 and GSK3β competitively interacted with the 12 armadillo repeats of β-catenin, a reaction that could inhibit the ubiquitin-proteasome degradation pathway of β-catenin in AQP1 overexpressed breast cancer cells." (PMID 32814878, 2021). "Therefore, GSK-3β and NF-κB may be cross targets for HER2+/HR+ breast cancer." (PMID 34977029, 2021).
breast cancer (continued). "Furthermore, we found that silencing of KIF3B decreased the expression of Dvl2, phospho-GSK-3β, total and nucleus β-catenin, then subsequent down-regulation of Wnt/β-catenin signaling target genes such as CyclinD1, C-myc, MMP-2, MMP-7 and MMP-9 in breast cancer cells." (PMID 33542902, 2020). "In breast cancer, PG could activate apoptosis by different signaling pathways including reducing Wnt/β-catenin, c-Jun N-terminal kinases/p38/RAD51 (JNK/p38/RAD51), or glycogen synthase kinase 3 beta/NAG-1 (GSK-3β/NAG-1), and inducing endoplasmic reticulum (ER) stress." (PMID 30282915, 2018). "Filtering specifically for breast cancer datasets that included prognostic stages (categories) based on the size of the tumor and extent of metastasis, we found correlations between cancer stage and the expression of negative (GSK3β) or positive (TCF4) regulators of Wnt/β-catenin signaling." (PMID 26202299, 2015). "Our results also highlight the importance of HER-2/neu or PI3K/Akt components, including GSK-3β, β-catenin, cyclin D1, Cdk4, p21WAF1, and p27KIP1, which may serve as future targets for the development of therapeutic strategies against HER-2/neu-overexpressing breast cancer." (PMID 22701509, 2012). "The correlation between GSK3β overexpression and survival was not significant in the case of patients with ER+/PR+ or HER2+ breast cancers." (PMID 30845991, 2019). "We first tested the expression of p-CREB, p-GSK3β, KLF5 and FGF-BP1 in a panel of breast cancer cell lines and found that p-CREB and p-GSK3β, KLF5 and FGF-BP1 are weakly or not expressed in non-TNBC cell lines compared with HCC1937." (PMID 28480051, 2017). "In our study, we demonstrated that GSK3β non-phosphorylatable mutant EZH2 (EZH22A, EZH2S363A, EZH2T367A) enhances cell migration and anchorage-independent growth in breast cancer and mammary epithelial cells." (PMID 27494834, 2016). "In addition, SHP-1 was found to inactivate signal transducers and activators of transcription 3 (STAT3) in HER2-overexpressing breast cancer cells (data not shown), thus indicating that the tumor-suppressive effects of SHP-1 cannot be fully compromised by EGFR/Ras/Erk/GSK3β pathway inactivation." (PMID 34591414, 2021).
Alzheimer disease (342 papers, 2005 to 2026). A progressive, neurodegenerative disease characterized by loss of function and death of nerve cells in several areas of the brain leading to loss of cognitive function such as memory and language. "Glycogen synthase kinase GSK‐3β, a highly conserved serine/threonine protein kinase, is implicated in the pathogenesis of diabetes, cancer, Alzheimer's disease, and atherosclerosis." (PMID 40718724, 2025). "In Alzheimer’s disease models, aberrant activation of GSK-3β has been associated with tau hyperphosphorylation, disrupting microtubule stability and thereby accelerating neurodegeneration." (PMID 41190025, 2025). "In Alzheimer’s disease models, the build-up of toxic amyloid-beta peptide aggregates has been associated with dysregulation of both Beclin1 and GSK3β." (PMID 41190025, 2025). "Highly expressed in neural tissues, GSK-3β has been implicated in several neurological disorders, including Alzheimer’s disease (AD), Parkinson’s disease (PD), and schizophrenia." (PMID 40520520, 2025). "Gsk3β, which is associated with neurodegenerative diseases, including Alzheimer’s disease, is predominantly expressed in the central nervous system and has been reported to phosphorylate SREBP-1c and promote its degradation upon activation." (PMID 38719751, 2024). "Glycogen synthase kinase 3-beta (GSK3-β) is a serine-threonine protease expressed in the brain, and its hyperactivity is considered the underlying cause of Alzheimer’s disease." (PMID 38191548, 2024). "GSK-3β is a key regulator of processes that underlie the development of Alzheimer’s disease; therefore, the search for its inhibitors has been widely studied." (PMID 38893493, 2024). "GSK3β is one of the main kinases that phosphorylates tau protein and has been linked to the pathogenesis of Alzheimer's disease (AD)." (PMID 37638222, 2023). "In summary, our study points out meridianins as a potential compound to treat neurodegenerative disorders associated with an hyperactivation of GSK3β such as Alzheimer’s disease." (PMID 35281935, 2022). "Deregulation of GSK‐3β is strongly implicated in a variety of serious brain conditions, such as Alzheimer disease, bipolar disorder and schizophrenia." (PMID 32463939, 2021). "The activation of GSK-3β is also associated with ageing, diabetes, Alzheimer’s disease and ischemia-associated vascular complications." (PMID 33946516, 2021). "In an Alzheimer’s disease (AD) mouse model, GSK-3β (glycogen synthase kinase 3β) causes phosphorylation of DRP1 at Ser40 and Ser44, which promotes its GTPase activity, thereby increasing mitochondrial division and neuronal apoptosis." (PMID 33498615, 2021). "Currently, there are no published reports linking GSK3b with tDCS-induced learning and memory, but a recent study reported that GSK3b is associated with Alzheimer’s disease." (PMID 31699891, 2019). "IL-2 and GSK3B proteins are T and natural killer (NK) cell regulators and have previously been associated with other neurodegenerative diseases such as Alzheimer’s disease, Parkinson’s disease and multiple system atrophy." (PMID 31123295, 2019). "In fact, abnormal GSK3β activity has been linked to schizophrenia, bipolar disorder, autism spectrum disorders, as well as Alzheimer's disease in which hyperactivity is commonly reported." (PMID 29449801, 2018). "In the Senescence Accelerated Mouse‐Prone 8 (SAMP8) mouse, an Alzheimer's disease mouse model, GSK‐3β inhibition caused NRF2 activation and decreased oxidative stress, together with reduced Tau phosphorylation and improved learning and memory." (PMID 29997171, 2018). "Increased activity of GSK3β has been implicated in neurodegeneration, particularly in Alzheimer’s Disease (AD)." (PMID 30574063, 2018). "Overexpression of GSK-3β in transgenic mice induces learning deficits and some features associated with Alzheimer’s disease." (PMID 30518432, 2018).
Alzheimer disease (continued). "With such pleiotropic function, Gsk3β is linked with many different diseases including diabetes, cancer, Alzheimer's disease, osteoporosis, and cardiac hypertrophy, and also with PD." (PMID 27503909, 2016). "The pathological characteristics of Alzheimer’s Disease (AD) have been linked to the activity of three particular kinases—Glycogen Synthase Kinase 3β (GSK3β), Cyclin-Dependent Kinase 5 (CDK5) and Extracellular-signal Regulated Kinase 2 (ERK2)." (PMID 24983862, 2014). "GSK-3β is widely implicated in several cellular pathways and, in the context of Alzheimer’s disease, associated with the hyperphosphorylation of the microtubule-associated protein tau." (PMID 23875003, 2013). "Polymorphisms in the gene encoding GSK-3β (GSK3B) have been associated with Alzheimer’s disease and frontotemporal dementia, and an epistatic interaction between GSK3B and MAPT has been associated with Parkinson’s disease and Alzheimer’s disease." (PMID 23951236, 2013). "GSK3β has been implicitly linked to diverse medical problems, such as diabetes, cancer, neurodegeneration and Alzheimer's disease." (PMID 23082110, 2012). "Dysregulation of GSK-3β expression leads to many pathological conditions, including diabetes (or insulin resistance), neuronal dysfunction, Alzheimer's disease, schizophrenia, Dopamine-associated behaviors, bipolar disorders, Parkinson's disease, and cancer." (PMID 22675363, 2012). "Recent evidence suggests that glycogen synthase kinase-3β (GSK3β) is implicated in both sporadic and familial forms of Alzheimer's disease." (PMID 20181016, 2010). "We have recently demonstrated that the phosphorylation of the 2N4R isoform of tau by GSK-3β causes arachidonic acid induced filaments to coalesce into larger structures similar to those purified from Alzheimer's disease." (PMID 19409104, 2009). "We have found that phosphorylation by GSK-3β is sufficient to cause tau filaments to coalesce into tangle-like aggregates similar to those isolated from Alzheimer's disease brain." (PMID 17598919, 2007). "For example, the rise in tAkt is of potential interest because it could inhibit GSK‐3β, a major tau phosphorylation regulator implicated in Alzheimer's disease progression." (PMID 39421964, 2025). "The PI3K/AKT/GSK-3β signaling pathway has been implicated in Alzheimer’s disease pathogenesis." (PMID 40732267, 2025). "Likewise, in vivo studies have shown that liraglutide helps prevent abnormalities in Akt and GSK-3β signaling and reduces tau phosphorylation associated with Alzheimer’s disease in the brains of diabetic mice." (PMID 40608828, 2025). "Because GSK3β is a crucial autophagy regulator, inhibiting it increases autophagic activity, essential for removing toxic protein aggregates associated with neurodegenerative diseases such as Alzheimer’s disease, Parkinson’s disease and Huntington’s disease." (PMID 41190025, 2025). "Similarly, the association between the investigated GSK3B single nucleotide polymorphism has been reported previously as twice as likely to occur in patients with Alzheimer's disease compared with healthy controls." (PMID 39668510, 2025). "The pathophysiological significance of GSK3β in neurodegeneration is largely attributed to its role in tau phosphorylation and amyloid-beta (Aβ) regulation, both of which are hallmark features of Alzheimer’s disease." (PMID 40573222, 2025). "The experimental investigation of the V317F mutated GSK-3β's effect on neurodegeneration may enhance the understanding of the biomarker potential of rs140668532 in Alzheimer's disease." (PMID 40520520, 2025). "Additionally, GSK-3β has been implicated in the pathogenesis of several neurodegenerative diseases, including Alzheimer’s disease, Parkinson’s disease, and mood disorders." (PMID 38660514, 2024).
Alzheimer disease (continued). "Genetic manipulation in mouse models has shown an antidepressant-like behavior upon GSK-3β knockdown in hippocampus, as well as cognitive, behavioral and biochemical changes associated with psychiatric disorders, including Alzheimer’s disease, BP and schizophrenia, upon GSK-3β overexpression." (PMID 38570518, 2024). "Gsk3β has also been identified as a potential risk factor for Alzheimer’s disease." (PMID 38719751, 2024). "GSK-3β and BuChE are prominent enzymatic targets associated with Alzheimer’s disease." (PMID 39204336, 2024). "Because Tyr216 of Gsk3β is phosphorylated upon mitochondrial translation inhibition, we focused on the tyrosine kinase Pyk2, which is involved in the pathogenic mechanism of neurodegenerative diseases such as Alzheimer’s disease." (PMID 38719751, 2024). "GSK3β is implicated in Alzheimer’s disease as a key mediator of cell death." (PMID 37790621, 2023). "Abnormal activation of GSK-3β has been associated with several neurological and psychiatric disorders that share developmental abnormalities and altered neurocircuitry maintenance, such as schizophrenia, bipolar disorder, autism, and Alzheimer’s disease (AD)." (PMID 34073043, 2021). "Moreover, like cdk5/p35, both PP1 and GSK-3β are strongly linked to the pathogenesis of Alzheimer’s disease." (PMID 31068217, 2019). "Glycogen synthase kinase-3 beta and cyclin-dependent kinase 5 have been identified as being involved in the pathological hyperphosphorylation of tau proteins, which leads to the formation of neurofibrillary tangles and causes Alzheimer's disease." (PMID 28179579, 2017). "GSK3β dysregulation, particularly hyperactivation, has been associated with various pathological conditions, including diabetes mellitus, inflammation, pulmonary hypertension and Alzheimer’s disease." (PMID 28196122, 2017). "GSK3B, a serine-threonine kinase, has been associated with Alzheimer’s disease and may regulate human aging via negative regulation of glucose homeostasis and Wnt signaling." (PMID 27060904, 2016). "We asked whether glycogen synthase kinase (GSK) 3α and GSK3β, which are implicated in diseases with neuropsychiatric symptoms, such as Alzheimer's disease, bipolar disease and schizophrenia, play a role in a spine structural plasticity." (PMID 26207897, 2015). "Given that GSK3B is implicated in development of both Alzheimer’s disease and schizophrenia, this suggests that at least part of the relationship of these disorders with reduced intracranial volume may reflect the impact of GSK3B on brain development." (PMID 23951236, 2013). "When hippocampal neurons are treated with the Aβ peptide (which extracellular accumulation is a hallmark of Alzheimer’s disease), there is an increase in cell apoptosis as well as in GSK-3β activity, whereas the intracellular levels of β-catenin and the transcription of Wnt-target genes are reduced." (PMID 24348333, 2013). "Moreover, the role of GSK-3β has been identified as one of the important enzymes regulating pathogenic mechanisms of Alzheimer's disease (AD) and Parkinson's disease (PD)." (PMID 21603026, 2011). "Interestingly, glycogen synthase kinase 3 beta is again highly associated with Alzheimer's disease and schizophrenia." (PMID 20230616, 2010). "Furthermore, the review points out that COX-2 enzymes have a relationship with kinase enzymes, including Cyclin Dependent Kinase 5 (CDK5) and Glycogen Synthase Kinase 3β (GSK3β), which are known to play a role in tau phosphorylation and are strongly associated with Alzheimer's disease." (PMID 37638222, 2023). "Variants of GSK3β gene have been implicated in relating to risk of Parkinson disease (PD), and studies in mice show that overexpression of this gene may be relevant to the pathogenesis of Alzheimer's disease." (PMID 29069795, 2017).